CD4 (CD4 molecule)
Diseases named in the same sentence as CD4 in open-access papers (continued):
Sharing a sentence is not in itself a finding about the gene and the disease.
chordoma (8 papers, 2021 to 2025). Chordomas are rare malignant tumors arising from embryonic remnants of the notochord in axial skeleton. "The correlation of CCR7 and other core T cell-associated genes with CD4+ and CD8+ T cell infiltration further supports their functional relevance in the chordoma immune microenvironment." (PMID 40386066, 2025). "Immunophenotype analysis 75 revealed elevated immune and MHC scores in chordoma tissue, although effector cell scores, which include activated and memory effector CD4 and CD8 cells, were paradoxically decreased." (PMID 40386066, 2025). "Shalin performed immunohistochemical (IHC) staining of 24 chordoma specimens and found CD4+ T lymphocyte infiltration in 21 patients and CD8+ T lymphocyte infiltration in only 11 patients." (PMID 38983929, 2024). "Several studies further analyzed the subgroups of the infiltrated CD4+ T cells and macrophages in chordoma." (PMID 38983929, 2024). "Dridi also found that macrophages and CD4+ T cells were the most abundant immune cell groups in chordoma tissues, followed by CD8+ T cells." (PMID 38983929, 2024). "Mean distance to chordoma cells was likewise similar among all T cells, CD4+ T cells: 97.40μm ± 185.07μm, CD8+ T cells: 92.52μm ± 167.04μm, and Tregs: 114.66μm ± 165.67μm." (PMID 36338744, 2022). "Additionally, CD4 T‐cell clusters had widespread overexpression of naïve markers (CCR7, SELL, LEF1 and TCF7), suggesting that CD4 T cells were in a naïve state in chordoma." (PMID 37784253, 2023). "Ten samples, including 5 chordoma I and 5 chordoma C tumors, with various immune scores, estimated with deconvolution method, were subjected to IHC staining against CD3, CD4 and CD8 (markers of T cell populations)." (PMID 37434245, 2023). "Remarkably, FN1 was upregulated, had more CNVs, and was more highly secreted by tumours, macrophages, CD4 T cells, CD8 T cells and fibroblasts in recurrent chordoma than in primary chordoma." (PMID 37784253, 2023). "The expression of FN1 in CD4 T cells, CD8 T cells, macrophages and CAFs was calculated, and FN1 was highly concentrated in recurrent chordomas." (PMID 37784253, 2023). "To confirm these results, we performed IHC on 10 primary samples and 10 recurrent samples and observed an enrichment of CD4 and CD8 cells in primary chordomas." (PMID 37784253, 2023). "Initially, we investigated the impact of FN1 on CD4 T cells and CD8 T cells by analysing the presence of CD3D, CD4, CD8 and FN1 in both primary and recurrent chordoma specimens." (PMID 37784253, 2023). "The implication of this discovery is that in recurrent chordoma patients, DCs, which have a vital function in activating CD8 and CD4 T cells in the TME, either become deactivated or are drawn away from the tumour location." (PMID 37784253, 2023). "In summary, our results suggest that primary chordoma displays attributes of a ‘hot’ tumour, with an increased presence of infiltrating CD4 T and CD8 T cells, whereas recurrent chordoma shows characteristics of a ‘cold’ tumour, along with EMT characteristics." (PMID 37784253, 2023). "The combined results suggest that FN1 secretion, specifically in CD4 T cells, CD8 T cells, macrophages and fibroblasts, may be increased in the TME of recurrent chordomas." (PMID 37784253, 2023). "Notably, FN1 was increased in tumour cells, CD4 T cells, CD8 T cells, macrophages and CAFs in recurrent chordomas." (PMID 37784253, 2023). "FOXP3 negative CD4+ cells were identified as helper T cells, co-localization of CD4 and FOXP3 in the absence of CD8 identified Tregs, and CD8+ cells were identified as T cells with potential cytotoxic activity against chordoma cells." (PMID 36338744, 2022).
chronic lung disease (8 papers, 2017 to 2024). According to the definitions of the American and British Thoracic Societies, including pulmonary functional tests, X-rays, and CT scans for items such as fibrosis, bronchiectasis, bullae, emphysema, nodular or lymphomatous abnormalities. "Secondary PjP prophylaxis can therefore be safely discontinued in asymptomatic patients on ART with plasma viral loads of <400 copies/mL, a CD4 count above 100 cells/μL, and no other risk factors for PjP, such as additional immunosuppression or chronic lung disease." (PMID 34118121, 2021). "Low peripheral blood CD4+ to CD8+ T-lymphocyte (CD4/CD8) ratio may reflect chronic inflammation in HIV and may be a marker of chronic lung disease in this population." (PMID 28122034, 2017).
colorectal adenocarcinoma (8 papers, 2017 to 2024). The most common type of colorectal carcinoma. "Colorectal adenocarcinoma was identified as the primary population in the tumor compartment, while immune cells, such as macrophages, mast cells, and CD4+ alpha beta T cells, were prevalent in the immune compartment." (PMID 38255741, 2024). "In contrast, high concentration of IL-24 robustly promoted CD4+ T cell proliferation, enhanced Th1 and Th17 response, and inhibited Treg response in colorectal adenocarcinoma patients." (PMID 31921658, 2019). "However, the current results suggested low percentages of Th1 and Th17 cells in both peripheral and tumor-infiltrating CD4+ T cells from colorectal adenocarcinoma patients." (PMID 31921658, 2019). "As anticipated, results showed correlations of immune cell markers in colorectal adenocarcinoma (COAD), specifically B cells, CD8+ T cells, CD4+ cells and M2 macrophages, with p < 0.05 considered significant." (PMID 35203586, 2022). "IL-24 mRNA expression was also notably down-regulated in both peripheral CD4+ and CD8+ T cells from colorectal adenocarcinoma patients when compared with those from healthy individuals (Student's t-tests, all P < 0.0001)." (PMID 31921658, 2019). "IL-24 receptor component, IL-20R1 and IL-20R2, was comparable in CD4+/CD8+ T cells between normal controls and colorectal adenocarcinoma." (PMID 31921658, 2019). "High-concentration of IL-24 promoted peripheral and tumor-infiltrating CD4+ and CD8+ T cell function, which provided novel therapeutic approaches to colorectal adenocarcinoma." (PMID 31921658, 2019). "IL-20R1 mRNA relative level was comparable in peripheral CD4+ and CD8+ T cells between colorectal adenocarcinoma patients and healthy individuals (Student's t-tests, P < 0.05)." (PMID 31921658, 2019). "Interestingly, the results showed specific correlations of immune cell markers in colorectal adenocarcinoma (COAD), with lower infiltration levels CD8+ T cells, CD4+ cells, and high M2 macrophages, with p < 0.05 considered significant." (PMID 36672201, 2023). "Thus, we hypothesized that IL-24 also modulates CD4+ and CD8+ T cell activity in colorectal adenocarcinoma patients in a dose-dependent manner." (PMID 31921658, 2019). "We did not observe differences in levels of CD4+ T cells, neutrophils, macrophages, or myeloid dendritic cells between GCA and colorectal adenocarcinoma as well as between GCA and IACSRCC." (PMID 34804955, 2021). "IL-20R1 and IL-20R2 mRNA was also comparable in tumor-infiltrating CD4+ and CD8+ T cells between colorectal adenocarcinoma tissue and non-tumor tissue (Student's t-tests, P < 0.05)." (PMID 31921658, 2019).
deep vein thrombosis (8 papers, 2013 to 2025). "In VTE, the immune landscape reflects sterile inflammation, with elevated levels of activated CD8+ T cells and effector memory CD4+ T cells, consistent with their roles in deep vein thrombosis." (PMID 41200172, 2025). "One death occurred on day 59 in a participant on efavirenz-ART who had been treated for deep vein thrombosis from day 33 and had CD4 count persistently below 50 since enrolment." (PMID 31429785, 2019). "Furthermore, previous research indicates that the occurrence of thrombosis increased number of Tregs, which consistent with our findings that Cluster 3 has the highest number of thrombotic events and also shows an increased numbers of Tregs and IL‐2 producing CD4+ T cells." (PMID 39965097, 2025).
delirium (8 papers, 2022 to 2025). A disorder characterized by confusion; inattentiveness; disorientation; illusions; hallucinations; agitation; and in some instances autonomic nervous system overactivity. "Conversely, 5 immune cells—namely, CD16 on CD14‐CD16+ monocytes, CD25 on CD39+ secreting Treg cells, CD39+ resting Treg cells % CD4 Treg cells, CD4 on activated Treg cells and TCRgd % T cells—were found to negatively regulate the risk of developing delirium (OR < 1)." (PMID 40891141, 2025). "Other cell types showed correlations primarily with delirium, such as memory CD4 + T cells expressing CXCR3, activated T cells, IgM + unswitched memory B cells, and exhausted B cells (CD21low CD38low)." (PMID 41219650, 2025). "Our findings highlighted the importance of biomarkers of inflammation and inappropriate CD4+ T cell activation in the onset of delirium." (PMID 36118695, 2022). "Our results indicate the role of cellular immunity and neuroinflammation in the development of delirium, and provide evidence that assessment of lymphocyte subsets, especially CD4+ T cells and CD4/CD8 ratio, is important for understanding this process." (PMID 36118695, 2022). "We suppose that delirium is associated with increased proinflammatory cytokines (such as IL-6 and TNF-α), which leads to inappropriate activation of peripheral CD4+ T cells and exacerbation of neuroinflammation in the brain, with BBB disruption." (PMID 36118695, 2022). "This suggests a potential role for CD4+ T cells in mediating neuroinflammation in delirium and providing potential biomarkers for delirium." (PMID 36118695, 2022). "The receiver operating characteristic curves and nomogram suggested a potential role for CD4+ T cells in mediating potential neuroinflammation of delirium." (PMID 36118695, 2022). "Recent studies have indicated that CD4 T cell subsets may be potential biological markers for delirium." (PMID 40765739, 2025). "Age, duration of physical restraint, CD4+ T cell count and CD4/CD8 ratio were reliable factors for predicting delirium in critically ill patients after cardiac surgery." (PMID 36118695, 2022). "Simultaneously, it proved that these two immune-related factors (CD4+ T cell count and CD4/CD8 ratio) were valuable to understand the pathophysiology of delirium." (PMID 36118695, 2022). "A nomogram revealed that age, cardiopulmonary bypass duration, CD4+ T cell count and CD4/CD8 ratio were independent predictors of delirium." (PMID 36118695, 2022). "Among the immune cells studied, 9, including CD123 on CD62L+ plasmacytoid DC, CD123 on plasmacytoid DC, and CD127 on CD45RA− CD4+ not Treg cells, showed a potential positive correlation with delirium (OR > 1)." (PMID 40891141, 2025). "There was a significant difference in CD4/CD8 ratio (median 2.31, IQR 1.00 in delirium group vs. median 1.28, IQR 0.83 in non-delirium group, p < 0.001)." (PMID 36118695, 2022).
dental caries (8 papers, 2010 to 2025). The decay of a tooth, in which it becomes softened, discolored, and/or porous. "This is similar to other studies that suggest a lower CD4 count being associated with higher dental caries experience." (PMID 35689234, 2022). "Some studies, including our previous study that focused only on children 8–15-year-old, demonstrated a positive association between dental caries and CD4 + cell count among children living with HIV." (PMID 33765997, 2021). "Taxa such as Actinomyces sp., Rothia mucilaginosa, Porphyromonas pasteri and Prevotella nanceiensis that were moderately or strongly associated with CD4 percent values were also associated with dental caries." (PMID 32616727, 2020). "Moreover, we identified an association between a higher CD4 count (> 350 cells/uL) with lower odds (0.4) of dental caries." (PMID 35689234, 2022). "Compared to HEU and HUU children, HI children were older, more likely to have lower CD4 lymphocyte counts and percentages, and experienced more dental caries and oral diseases (p < 0.05)." (PMID 32616727, 2020). "The results indicated that salivary gland enlargement (315±156), dental caries (323±54), angular cheiliti (460±310), and erythematous candidiasis were accompanied by the least CD4 count, respectively." (PMID 23346337, 2010). "A higher CD4 count was associated with the presence of dental caries (OR 0.403, 95% CI 0.175–0.932) although it was not significant in multivariate analysis." (PMID 35689234, 2022). "The prevalence of dental caries was higher among those with lower CD4 cell counts (p <0.001)." (PMID 31618211, 2019). "The consistent and significant effect of immunosuppression (CD4 percent values) on the salivary microbiota regardless of age might explain the increased risk for dental caries in HI populations, as we and others have previously reported." (PMID 32616727, 2020). "The traits of the following six immune cells (activated & secreting Treg % CD4, IgD+ CD38dim AC, secreting Treg % CD4, CD62L−DC % DC and secreting Treg % CD4 Treg) were positively correlated with dental caries development (OR > 1, P < 5.0E-02)." (PMID 41444670, 2025). "This may suggest a correlation between dental caries and viral load, as CD4 + cell count has a negative correlation with viral load." (PMID 33765997, 2021).
E. coli infection (8 papers, 2013 to 2025). "In contrast to the other categories of bacterial infections, the E. coli infection group had significantly increased naive B cells and naive CD4 T cells and significantly reduced plasma cells and neutrophils." (PMID 38066783, 2023). "We found that percentages of CD4+CD25+Foxp3+ Tregs in CD4+ PTLN cells were significantly elevated by E. coli infection, along with the enhanced IL-10 secretion." (PMID 23536867, 2013). "In addition, we found that the deficiency of DOCK2 significantly augmented the frequencies and numbers of CD4+IFN-γ+ inflammatory Th1 cells in the spleens, lungs, and livers in response to E. coli infection, resembling the phenotypes of LPS challenge." (PMID 40510337, 2025). "Depleting CD8 or CD4 T cells, respectively, prior to LPS exposure neither affected the difference between sensitive and tolerant animals to organ damage nor the bacterial load upon E. coli infection." (PMID 36178806, 2022).
echinococcosis (8 papers, 2014 to 2023). A parasitic infection caused by tapeworm larvae of Echinococcus. "In fact we have found in this study a strong association with HAART in patients with CD4+ cell count less than 200/μl and seropositivity to echinococcosis." (PMID 25188395, 2014). "multilocularis activity, promoting cytokine secretion and enhancing anti-echinococcosis immune responses by increasing the proportion of CD4+ T lymphocytes." (PMID 34143400, 2022). "Subsequently, hepatic echinococcosis can induce the expression of PD-1 on the surface of liver-specific CD4+ and CD8+ effector T cells by secreting antigens and using surface molecules." (PMID 34248983, 2021). "Thiacloprid enhanced the activity of CD4+T lymphocytes, promoted the expression of anti-echinococcosis related cytokines in serum, and promoted host–lesion microenvironment collagen deposition." (PMID 34488852, 2021). "Previous observations have come up with the following associations between human echinococcosis and HIV: Echinococcosis usually leads to a TH2 (T helper)-dominated immunomodulation, and suppression of the CD4+ T-cell population, as is typical in HIV infection." (PMID 31013827, 2019). "Higher serum CXCL10 levels may recruit more CD4+ T cells for metastasis to the liver, leading to a more severe immune response; echinococcosis might have a similar mechanism." (PMID 36034715, 2022). "Since CD4+ T-cells are usually able to limit cyst growth to a certain extent, complicated clinical forms of echinococcosis such as neuronal involvement, multifocal cysts, and racemic forms are observed more often in HIV-infected individuals with impaired immune function." (PMID 31013827, 2019). "During echinococcosis, the impaired host immune response is paralleled by an increased expression of TGF-β signaling components in periparasitic host cells and tissues with the expansion of tolerogenic CD4+ CD25+ Foxp3+ Treg cells." (PMID 32457746, 2020). "In the group with CD4+ cell counts between 200–500 cells/μl, the seroprevalence rate was higher in patients not on HAART for cysticercosis and for echinococcosis." (PMID 25188395, 2014).
enterocolitis (8 papers, 2006 to 2024). An inflammatory process affecting the small intestine and colon. "Adoptive transfer of CD4+ T cells overexpressing a dominant-negative form of IL-10RA into immunodeficient mice causes the development of spontaneous enterocolitis." (PMID 32303238, 2020). "Classical studies reported that the enterocolitis in IL-10-deficient mice is associated with uncontrolled cytokine production by activated macrophages and CD4+ Th1-like T cells." (PMID 22400037, 2012). "Macaque 1494 was euthanized approximately 2 years after SIVmac055 challenge with clinical symptoms of severe enterocolitis and diarrhea, and marked loss of CD4+ T cells." (PMID 17184540, 2006). "This phenomenon is attributed to the presence of CD25+FoxP3+ regulatory T cells within the CD4+CD45RBLo population and adoptive transfer of CD4+CD25− T cells has thus been proposed as the most suitable T cell transfer model of enterocolitis." (PMID 24616886, 2014). "Notch in CD4 as well as CD8 T cells regulates crucial effector functions in multiple distinct cell types, which might mask the development of enterocolitis in Rbpj−/− mice." (PMID 31071093, 2019).
Erythema (8 papers, 2014 to 2025). Redness of the skin, caused by hyperemia of the capillaries in the lower layers of the skin. "In particular, CD4+ T lymphocyte infiltration in the EC erythema group and CD8+ T lymphocyte infiltration in the PPD induration group were significantly different from those in the PBS group." (PMID 38068935, 2023). "T lymphocyte infiltration at the sites of PPD induration and EC erythema, including CD4+ T lymphocytes and CD8+ T lymphocytes, was noted to be higher in comparison to that in the PBS group." (PMID 38068935, 2023). "Old human subjects exhibited decreased erythema and induration, CD4+ and CD8+ T-cell infiltration, and attenuated global gene activation at the site of cutaneous VZV antigen challenge compared with young subjects." (PMID 29155150, 2018). "The expression of CCL5 in PPD induration was reported to be significantly higher than in EC erythema, which could increase CD4+ and CD8+ T infiltration, consistently with our immunohistochemical results." (PMID 38068935, 2023). "Our data also showed robust activation of CD4+ T and CD8+ T in PPD induration- and EC erythema-induced DTH reactions, indicating that specific antigenic peptides can be processed and presented on MHC-I and MHC-II molecules after antigen treatment by APCs." (PMID 38068935, 2023). "However, either CD4+ or CD8+ T-cell depletion in infected and vaccinated mice had significantly decreased LST reactions with less erythema and thickness." (PMID 37919280, 2023). "Interestingly, n-3PUFA increased the infiltration of CD4+ and CD8+ T cells but did not alter the erythemal response, either the sunburn threshold or the resolution of erythema, as assessed by spectrophotometric hemoglobin index readings." (PMID 31518521, 2019).
hepatic granuloma (8 papers, 2015 to 2024). A granuloma located in the liver. "The LB group has the highest relative prevalence of CD4+ T cells, alongside smaller hepatic granulomas." (PMID 39466851, 2024). "The major Th2 cytokine, IL-4, secreted by CD4+ T cells also contributes to the development of hepatic granulomas." (PMID 34977224, 2021). "These mice have fewer and smaller hepatic granulomas and an increase in CD4+IL-4, IL-5, IL-13+, and CD4+Foxp3+IL-10+ cells that correlate with collagen deposition and wound healing." (PMID 27648452, 2016). "However, depletion of CD4+CD25+ Tregs in SjHSP60-injected mice significantly enhanced the formation of hepatic granulomas." (PMID 26418003, 2015).